AKT1 (AKT serine/threonine kinase 1)
Diseases named in the same sentence as AKT1 in open-access papers (continued):
Sharing a sentence is not in itself a finding about the gene and the disease.
breast cancer (continued). "Among the several miRNA–mRNA target interactions in TNBC and/or breast cancer in general, the cancer driver genes, such as BRCA1, ESR1, PTEN, and AKT1, were observed." (PMID 37685851, 2023). "Based on an extensive literature survey, three important target receptors—Akt1, COX2 and HER2—were chosen for molecular docking studies due to their importance in breast cancer progression." (PMID 37894581, 2023). "AKT1 phosphorylates SIRT6 at S338 and enhances the degradation of SIRT6 through the ubiquitin-proteasome pathway in breast cancer cells." (PMID 37607939, 2023). "We provide novel information on the fact that Haliclona fascigera extract exhibits anticancer properties against breast cancer via the activation of BIRC5, AKT1, MAPK, and TNFRSF1A genes." (PMID 37687120, 2023). "Additionally, AKT1-3 mutations and/or amplifications, PDK1 amplification, PTEN and TSC1/2 inactivating mutation, and deletion or epigenetic silencing, which cause hyperactivation of the pathway, have also been found in breast cancer and have been suggested to hold prognostic or predictive value." (PMID 36901954, 2023). "A molecular docking analysis using AutoDock Vina software demonstrated the stable binding of WPPNYQW to the active sites of overexpressed EGFR, PI3K, AKT1, and CDK4 proteins in breast cancer." (PMID 37908979, 2023). "In some cases, biopsies were taken many years before the participant entered the FAKTION trial, but the original tumour PIK3CA, AKT1, and PTEN status appeared to define the efficacy of capivasertib for advanced breast cancer." (PMID 35671774, 2022). "When counted together, 71.8% of breast cancers, which include 42.1% PPAPA and 29.7% PPAPA/TP53I tumors, contain the PTEN-PI3K-AKT1 pathway activated by genomic alterations of Pten, PIK3CA (H1047R & E545K), and AKT1 (E17K)." (PMID 34975329, 2022). "The clinically available AKT1 inhibitor, MK-2206, can stabilize TWIST1 and enhance EMT and metastasis in breast cancer cells." (PMID 36115849, 2022). "A study, which recently reported shared neoantigen targets in breast cancer such as PIK3CA H1047R E545K N345K and AKT1 E17K, was conducted on unspecified breast cancer samples." (PMID 36298462, 2022). "The AKT protein kinases consist of three isoforms; AKT1, AKT2, and AKT3, and each isoform has been proposed to have a distinct biological role in mammary tumor progression." (PMID 35441158, 2022). "All patient-specific subnetworks contained relevant drug targets that have been largely studied in breast cancer (e.g., ERBB2, ESR1, EGFR, AKT1)." (PMID 33706810, 2021). "Moreover, although the increased FN1 expression which followed with the activite of p-Akt1 had observed in this study, however, the opposite role of p-Akt1 on regulating FN1 expression also reported in breast cancer cells, the interaction between FN1 and p-Akt1 may be have a more complex manner." (PMID 34758823, 2021). "Amplification of AKT1, AKT2 and AKT3 has been reported in gastric, ovarian, pancreatic and breast cancers, glioma and melanoma." (PMID 34419139, 2021). "Evidence supports that radiation increases phosphorylated AKT1 and AKT2 in the breast cancer MCF7 mammospheres CD44+/CD24−/low-expressing cells, whereas the inhibition of the AKT signaling pathway sensitizes MCF7 mammosphere cells to ionizing radiation." (PMID 34217266, 2021). "Like AKT1, the role of the AKT2 isoform in breast cancer is complex and there are conflicting reports in the literature." (PMID 33498407, 2021). "Next, the expression of PTEN, p-AKT1, p-CREB, and PDGFRα in invasive breast cancer tissues and the corresponding adjacent normal tissues was assessed by Western blot." (PMID 33568640, 2021). "Inhibition of AKT1 in MMTV-ErbB2/neu and MMTV-PyMT-induced mouse mammary tumors results in diminished tumor development due to lower expression of Ki-67 and cyclin D and increased apoptosis." (PMID 33498407, 2021).
breast cancer (continued). "To examine the importance of AKT1-mediated phosphorylation and RNF167-mediated degradation of CASTOR1 in breast cancer cells, we overexpressed Flag-CASTOR1 WT, S14A, and S14D in HCC1569, MCF7, and T47D cells." (PMID 33594058, 2021). "A cBioPortal analysis shows ≈50% of breast cancers with genomic aberrations in PIK3CA, AKT1, AKT2, AKT3, and/or ESR1,suggesting relevance of this signaling axis in breast cancer." (PMID 33498407, 2021). "Ipatasertib, another AKT inhibitor which was initially tested in TNBC, has been evaluated in HR-positive, HER2-negative advanced breast cancers through the IPATunity 130 randomized phase III trial, among patients with PIK3CA/AKT1/PTEN altered tumors." (PMID 34948307, 2021). "AKT1 (Gene Entrez ID 207) and TSG101 (Gene Entrez ID 7251) are the breast cancer gene markers that eDRW+ has detected for the GSE1456 and GSE1561 datasets." (PMID 34573857, 2021). "Those genes are frequently altered in different cancers, including AKT1, EGFR, KRAS, and STK11 in lung cancer and AKT1, BRCA2, ERBB2, and PIK3CA in Breast cancer." (PMID 34906079, 2021). "A recent study showed that Rho GTPase activating protein 29 (ARHGAP29) interacted with Akt1 and knockdown of ARHGAP29 decreased invasion of breast cancer cells." (PMID 34298660, 2021). "The results of comparison analysis showed that Akt1 and CCND1 (cyclinD1) were significantly different in different types of breast cancer." (PMID 33911067, 2021). "While different studies revealed different results regarding the involvement of AKT1 and AKT2 in mammary carcinomas, AKT3 dysfunctions are often correlated with triple negative breast cancer." (PMID 34199634, 2021). "A total of 4,895 breast cancer cases from 2015 to 2019 with available PIK3CA, AKT1, and PTEN NGS results were reviewed." (PMID 32983983, 2020). "The PI3K/AKT pathway is a well-established oncogenic pathway, and AKT1 and AKT2 have repeatedly been shown to differentially regulate breast cancer cell proliferation and invasion." (PMID 32201539, 2020). "Gene deletion of AKT1 resulted in reduced cellular migration in vitro, reduced metastasis of HER2-induced breast cancers, and reduced phosphorylation of the tumor suppressor tuberous sclerosis complex 2 (TSC2) in a murine in vivo model." (PMID 33291460, 2020). "The ratio of AKT1 and AKT2 has been reported to regulate EMT and CSC traits through regulation of miR‐200s in breast cancer." (PMID 31600013, 2020). "Knockdown of YAP1 in ERα+ MCF7 breast cancer cells led to reduced expression of ERα and FOXM1, cell cycle arrest, and senescence and inhibition of AKT1 and increased activity of FOXO3A." (PMID 32967092, 2020). "It has been reported that the ratio of AKT1 and AKT2 expression regulates EMT and CSC properties in a breast cancer model." (PMID 31600013, 2020). "A striking example are the roles of AKT1 and AKT2 in breast cancer where AKT2 enhances migration and invasion, whereas AKT1 inhibits these processes." (PMID 33045011, 2020). "For example, AKT silencing restored formation of IR-induced BRCA1 foci in breast cancer cells, whereas HR-related proteins (e.g., BRCA1 and Rad51) sequestered in the cytoplasm upon activation of AKT1." (PMID 33266502, 2020). "Because AKT1 and AKT2 have been shown to differentially regulate invasion and proliferation in breast cancer 35,36, we used isoform-specific antibodies to measure AKT1 and AKT2 phosphorylation at S473." (PMID 32201539, 2020). "According to a previous study, specific activation of AKT-1 is a contributor to EZH2-induced phenotype, and the overexpression of EZH2 induces activation of AKT-1 and BRCA1 inhibition in breast cancer, which was consistent with our findings." (PMID 31830649, 2020). "The expression and kinase activity at the protein level mainly depend on the subtype of breast cancer e.g. AKT3 is highly expressed in TNBC, whereas expression of AKT1 correlates with positive ER status." (PMID 31752925, 2019).
breast cancer (continued). "For example, somatic mutations in genes PIK3CA and AKT1 were identified as driver events for breast cancer, suggesting malfunction of PI3K/AKT pathway in cancer." (PMID 30682127, 2019). "The LOTUS study reported that ipatasertib in combination with paclitaxel improved PFS in patients with PIK3CA/Akt1/PTEN-altered TNBC, suggesting that PIK3CA/Akt1/PTEN alterations can also be biomarkers of response to ipatasertib in patients with breast cancer." (PMID 31227862, 2019). "The anti-migratory and anti-invasive effect of AKT1 in colorectal carcinoma cells is mediated by a decrease in MMP9 expression, as it was also observed in breast cancer cells." (PMID 31752925, 2019). "The dichotomy of AKT1 in positively regulating proliferation and negatively regulating migration also suggests a stadium-dependent role of the AKT isoforms in breast cancer and was reviewed by Toker and Yoeli-Lerner in 2006." (PMID 31752925, 2019). "This association was evidenced by the results indicating that knockdown of Notch1 and Akt1 abrogates Nanog-mediated radioresistance and Nanog-mediated high ALDH activity in breast cancer cell lines." (PMID 30845764, 2019). "In agreement with us, both AKT1 and ERBB2 have already been found to be highly expressed in ER+ recurrent breast cancer as possible genes involved in the mechanism of resistance to Tamoxifen." (PMID 31781306, 2019). "The role of AKT1 and AKT3 in breast cancer should be studied as well, because these isoforms have distinctive and non-redundant activities." (PMID 31357505, 2019). "We here disclose a novel Akt1/PIKfyve/EGFR/β-catenin signaling pathway, which contributes to the metastasis of breast cancer." (PMID 30445978, 2018). "We recently showed that progesterone decreases the activation of multiple kinases like EGFR, AKT1, and ERK1/2 in breast cancer cells, leading to suppression of cell migration." (PMID 30337371, 2018). "The present study was designed to analyze the specific role and signaling of AKT1 and AKT2 in regulating the different stages of breast cancer progression in two human ductal breast cancer cell lines growing in culture and in xenografts." (PMID 28287129, 2017). "Akt1 has been reported to impair the nuclear localization and foci formation of BRCA1/Rad51 as well as HR repair in normal tissue and breast cancer cells." (PMID 29156644, 2017). "In breast cancer cells, the inhibition of the PI3K/AKT1/mTORC1 pathway or knockdown of IGF1R suppresses the EMT program, reducing stem cell niches." (PMID 28880250, 2017). "AKT1 is a downstream mediator of the PI3K / PTEN / AKT / mTORC1 pathway, which has been suggested to play crucial roles in the development of breast cancer." (PMID 28301567, 2017). "This is consistent with the established role for AKT1 in inhibiting and AKT2 in promoting breast cancer cell migration and metastasis." (PMID 28082369, 2017).
breast cancer (continued). "Regarding AKT1 and AKT2 studies, several transgenic mouse models with mammary carcinomas have been developed, and they showed diverse results." (PMID 28287129, 2017). "For example, overexpression of AKT1 was shown to inhibit motility, whereas overexpression of AKT2 promotes motility and migration in breast cancer cells, the latter resulting in increased formation of metastases." (PMID 26741489, 2016). "Since opposing effects of AKT1 and AKT2 were described in breast cancer cell migration, AKT1 suppressing invasion and AKT2 enhancing it, we analyzed phosphorylation of AKT1 and AKT2, in addition to T308 in the RUNX2 knocked down melanoma cell lines." (PMID 27102439, 2016). "As an example, all four genes (AKT1, BCL2, ERBB2 and VEGF) identified to change radial position after in vitro induction of early breast cancer were expressed at similar levels in the normal as compared to tumor cells." (PMID 27507988, 2016). "In breast cancer cells, OA was shown to stimulate proliferation, and to rapidly increase cytosolic Ca2+ and activate PI3K and AKT1." (PMID 27894086, 2016). "Specifically, both phospho-mimetic AKT1(T308D/S473D) and Myr-AKT1 transgenes accelerate HER2-driven mammary tumor formation." (PMID 27004402, 2016). "Mutant AKT1-E17K has been shown to transform murine embryo fibroblasts but its role in epithelial tumorigenesis remains unclear because it apparently exerts minimal effects in immortalized breast MCF-10A epithelial cells but is transforming in knocked-in breast cancer MCF-7 cells." (PMID 26053093, 2015). "Meanwhile, down-regulation of Akt1 resulted in the suppression of Bcl-2, P-gp and COX-2, and increase of Bax expression in breast cancer cells." (PMID 26359357, 2015). "Comparison of copy number analysis of HMEC, SUM149PT, SUM1315MO2 adherent cells revealed high copy numbers of AKT1, AURKA, CDK4, EGFR1, PAK1 and MYC in breast cancer cells as compared to HMEC cells." (PMID 26608463, 2015). "Among the genes amplified in the focal regions were a cluster of HOX genes (HOXA7, HOXA9, HOXA10, HOXA11) on 7p15, AKT1 (14q32.33), IGF1R (15q26.3), ERBB2 and NEUROD2 (17q12), all of which have been reported in primary breast cancers." (PMID 24489661, 2014). "We describe a quantitative and comparative dataset focused on immediate-early signaling that regulates the AKT (AKT1/2/3) and ERK (MAPK1/3) pathways in a canonical panel of well-characterized breast cancer lines." (PMID 24655548, 2014). "ErbB2/ErbB3 receptor activation, which occurs frequently in breast cancer, induces PI3K and Akt1 kinase activity." (PMID 24658544, 2014). "Since Ak1 and Akt2 were consistently expressed in the mammary tumors, MTB-IGFIR mice were crossed with Akt1−/− and Akt2−/− mice to determine the roles of Akt1 and Akt2 in mammary tumorigenesis." (PMID 23919516, 2013). "A recent study shows that, at 10 μM, H-89 is able to inhibit intracellular S. typhimurium growth in the human breast cancer cell line MCF7 and the inhibition of host cell’s Akt1 by H-89 is most likely the attributing factor." (PMID 23554945, 2013). "In particular, AKT1 and AKT2 opposing functions on migration of breast cancer epithelial cell lines have been firmly established." (PMID 23165443, 2013). "Mammary tumors with normal levels of Akt1 and Akt2 had similar levels of the IGF-IR as mammary tumors null for Akt1 or null for Akt2." (PMID 23919516, 2013). "The results show that a number of important cancer genes for each cancer type are ranked highly by TARGETgene, such as AKT1 (rank #1), SRC (rank #10), and ERBB2 (rank #25) in breast cancer." (PMID 22952662, 2012). "Conclusively, the group of Muller demonstrated that AKT1 induced tumor growth, while AKT2 promotes metastasis of ErbB2-induced breast cancer in vivo." (PMID 23167739, 2012).
breast cancer (continued). "For example, AKT1 knockdown induces cell migration and EMT in breast cancer cell lines, while AKT2 knockdown suppresses these behaviors." (PMID 22666248, 2012). "Meaburn and Misteli analyzed the radial distribution of four genes related to cell survival, mobility and migration, namely AKT1, VEGF, ERBB2, and FGFR1 in a cell-model of breast cancer." (PMID 20958983, 2010). "Since PKB (AKT1) is upregulated in cancers, we overexpressed PKB in human SV40-immortalized fibroblasts (GC92) at a level that is comparable with that observed endogenously in a panel of breast cancer cells." (PMID 40479710, 2025). "Based on the CAPItello-291 phase III trial results, capivasertib in combination with fulvestrant has been approved for patients with hormone receptor-positive/human epidermal growth factor receptor 2-negative advanced breast cancer harboring one or more PIK3CA, AKT1, and/or PTEN alterations." (PMID 40597213, 2025). "In breast cancer tissues and cells, HDAC8 expression is up‐regulated, and HDAC8 interacts with AKT1, deacetylating it at lysine 426 and activating AKT1, thereby increasing GSK‐3β phosphorylation and promoting its degradation, which triggers the spread and EMT of breast cancer cells." (PMID 39778006, 2025). "Combining fulvestrant (an Estrogen Receptor (ER) degrader) with the PI3K-AKT signalling inhibitors alpelisib (PI3Kαi) or capivasertib (AKTi) provides benefit in ER+ breast cancer (BC) patients with PIK3CA altered and PIK3CA, PTEN and AKT-1 altered tumours respectively." (PMID 40263319, 2025). "In addition to Fulvestrant, Capivasertib was added to the treatment regimen in patients with HR+ advanced breast cancer with alterations in PIK3CA, AKT1, or PTEN." (PMID 40943615, 2025). "In endocrine-resistant ER+HER2- breast cancer, while hyperactivated AKT1 suppresses cGAS-STING signaling by binding to TBK1 and disrupting the TBK1/STING/IRF3 complex, combining AKT1 inhibitors with STING agonists restores innate immune activation and impairs tumor growth in preclinical models." (PMID 41573551, 2025). "Data from CAPItello-291 have led to the regulatory approval of capivasertib–fulvestrant in patients with HR-positive/HER2-negative advanced breast cancer and one or more tumor biomarker alterations (PIK3CA, AKT1 or PTEN) in several countries, including in Japan and the US." (PMID 39379782, 2025). "Expert Panel Recommendations: Based on the CAPItello‐291 study, capivasertib combined with fulvestrant is recommended for patients with locally advanced or metastatic HR‐positive/HER2‐negative breast cancer who exhibit any gene alterations in PIK3CA, AKT1, or PTEN." (PMID 40206206, 2025). "Additionally, for advanced breast cancer patients with PIK3CA, AKT1, or PTEN alterations who have previously received CDK4/6i, capivasertib in combination with fulvestrant presents a viable treatment option." (PMID 40206206, 2025). "Notably, AKT1, ERBB2 (HER2), CDK4, and CCNE1 are significantly amplified in tumor samples while PIK3CA displays the lower expression level in breast cancer." (PMID 40725120, 2025). "The AKT1 and AKT2 isoforms play dominant roles in breast cancer." (PMID 41408399, 2025). "Regardless of its specific function, AKT1 has a well-documented correlation with breast cancer and is an appropriate target for pharmaceutical intervention." (PMID 39057065, 2024). "PIK3CA, the most frequently mutated oncogene in luminal breast cancer, can affect the PAM signaling pathway regardless of receptor status, while 4% of cases have mutations of AKT-1 and PTEN." (PMID 38504785, 2024).